RP9P (RP9 pseudogene)
Gene: Transcribed unprocessed pseudogene on chromosome 7 (32,916,815 to 32,943,038, reverse strand). Ensembl gene ENSG00000205763.
Diseases named in the same sentence as RP9P in open-access papers:
RP9P is named in the same sentence as 3 diseases in open-access papers, as found by Europe PMC text mining. Sharing a sentence is not in itself a finding about the gene and the disease. The quoted sentences say what the papers report.
colorectal cancer (1 paper, 2022). A primary or metastatic malignant neoplasm that affects the colon or rectum. "RP9P promotes colorectal cancer progression by regulating the miR-133a-3p/FOXQ1 axis." (PMID 35600345, 2022). "The long non-coding RNA (lncRNA) RP9 pseudogene (RP9P) is a pseudogene-derived lncRNA that has never been reported in cancer, and its function underlying tumorigenesis in colorectal cancer (CRC) remains unknown." (PMID 35600345, 2022).
cancer (3 papers, 2021 to 2022). A tumor composed of atypical neoplastic, often pleomorphic cells that invade other tissues. "To investigate the effect of RP9P, we analyzed TCGA data (COADREAD) of 383 CRC and 51 non-cancer tissues." (PMID 35600345, 2022). "RP9P is a pseudogene-derived lncRNA, located at chromosome 7:32,916,815-32,943,176, that has never been reported previously in cancer." (PMID 35600345, 2022). "However, for the remaining pseudogenes (DDX12P, NCF1C, RP9P, and YWHAZP4), there were no reports on their biological functions in cancers." (PMID 36272991, 2022).
tumor (3 papers, 2022 to 2025). "Furthermore, downregulating miR-133a-3p expression rescued the tumor-suppressive effect caused by RP9P knockdown alone." (PMID 35600345, 2022). "We also confirmed that downregulating the RP9P level suppressed tumor growth in xenograft nude mice." (PMID 35600345, 2022). "RP9P directly interacted with miR-133a-3p, and miR-133a-3p downregulation abrogated the tumor-suppressing effect of RP9P knockdown." (PMID 35600345, 2022). "Furthermore, miR‐133a‐3p downregulation counteracted the tumor‐suppressive effects of RP9P knockdown, highlighting the RP9P/miR‐133a‐3p/FOXQ1 axis as a critical pathway in CRC progression." (PMID 40556338, 2025). "Except for GVINP1 and NCF1C, the expression of the other 5 prognosis-related DE pseudogenes (DDX12P, FER1L4, NSUN5P2, PLEKHA8P1 and RP9P) were higher in tumor tissues than in cutting edge normal tissues, which was totally consistent with the results of TCGA samples." (PMID 36272991, 2022).